CD4 (CD4 molecule)
Diseases named in the same sentence as CD4 in open-access papers (continued):
Sharing a sentence is not in itself a finding about the gene and the disease.
HIV-1 infection (continued). "In the context of HIV-1 infection, CD4+ T cells serve as the primary targets, the alteration of their miRNA profiles is much more directly associated with the development of the illness." (PMID 40296890, 2025). "The presence of HIV-1 in platelets has harmful effects on the immune system, particularly on CD4+ T cells during HIV-1 infection." (PMID 39354676, 2025). "In conclusion, CD4+ T cells need to directly interact with macrophages to increase HIV-1 infection, and macrophage-derived HIV-1 is primarily transmitted to CD4+ T cells via cell-to-cell contact." (PMID 40130873, 2025). "Pyroptosis, a pro-inflammatory form of cell death driven by caspase-1 activation and gasdermin D pore formation, is a major driver of CD4+ T cell depletion during HIV-1 infection." (PMID 40072080, 2025). "Over time, chronic HIV-1 infection leads to the progressive depletion of CD4+ T cells, especially in untreated individuals." (PMID 40699766, 2025). "HIV-1 infection of primary CD4+ T cells increases the m6A levels and nuclear accumulation of PLIN3 mRNA but decreases translation of the message in the cytoplasm." (PMID 41085277, 2025). "CD4+ T cell count decline during HIV-1 infection and SIV infection in macaques leads to immune system failure and fatal immunodeficiency." (PMID 39842407, 2025). "As an ISG, LY6E has been shown to enhance the infection of Dengue virus, ZIKV, yellow fever virus, IAV, and VSV, while having dual effects on HIV-1 infection, promoting infection in CD4-high T cells and inhibiting it in CD4-low T cells." (PMID 40901862, 2025). "Together, we here present a quantitative unbiased expression analysis of 332 membrane receptors in primary CD4+ T cells and their modulation as a consequence of HIV-1 infection." (PMID 40911682, 2025). "Dysfunctional telomere-induced 53BP1 was higher in primary CD4+ T cells after HIV-1 infection than in uninfected CD4+ T cells." (PMID 40244051, 2025). "To identify key TFs and construct a gene regulatory network associated with HIV-1 infection, we integrated gene expression and chromatin accessibility data from HIV-1 RNA+ CD4+ T cells." (PMID 40838493, 2025). "We confirmed significant correlations between neutralization score and viral load, CD4, duration of HIV-1 infection, viral diversity, and black ethnicity." (PMID 40802847, 2025). "As anticipated, CD4-targeting shRNA completely blocked HIV-1 infection, validating the screening approach." (PMID 40029073, 2025). "In HIV-1 infection, the FAS rs1800682 (A/G) and FAS rs2234767 (G/A) polymorphisms were associated with the apoptosis of CD4+ T lymphocytes and disease progression in people living with HIV-1." (PMID 39859379, 2025). "Apoptosis in CD4+ T cells during HIV-1 infection can be induced through the action of several viral proteins like Vpr, which disrupts mitochondrial membrane potential, leading to the activation of caspases and cell death." (PMID 40072080, 2025). "These anti-HIV-1 genes include an shRNA against CCR5 HIV-1 co-receptor and C46 fusion inhibitor to protect cells against HIV-1 infection, and a truncated CD4-based CAR with 4-1BB costimulatory domain (D1D2CAR 4-1BB) to attack HIV-1-infected cells." (PMID 40503012, 2025). "MicroRNA-9 levels in CD4+ T cells from people with persistent HIV-1 infection are lower than in healthy people or LTNPs." (PMID 40296890, 2025). "Here, we demonstrate that HIV-1 infection of activated primary CD4+ T cells promotes the interaction between the m6A writer complex subunits methyltransferase-like 3 and 14 (METTL3/METTL14)." (PMID 41085277, 2025). "We also found that 2P23-PRO140SC displayed synergistic effects with the previously designed bispecific inhibitors 2P23-iMab and m36.4-PRO140, which potently blocked HIV-1 infection through CD4-anchoring or CCR5 anchoring." (PMID 40130879, 2025).
HIV-1 infection (continued). "The authors concluded that the mechanism by which THC suppresses HIV-1 infection includes a reduction in HIV receptor (CD4, CCR5, and CXCR4) expression on the cell surface, which diminishes entry efficiency." (PMID 40141240, 2025). "The GSEA results revealed that interferon-gamma and interferon-alpha responses were upregulated in all CD4+ T cell subtypes upon HIV-1 infection." (PMID 40838493, 2025). "Overall, HIV-1 infection leads to a reduction in CD4+ T cell counts in treatment naïve PWH, including PWHEC." (PMID 40936922, 2025). "Acute HIV-1 infection (AHI) is a transient period where the virus causes evident damage to the immune system, including an extensive apoptosis of CD4+ T cells associated with a high level of activation and a major cytokine storm to fight the invading virus." (PMID 40143294, 2025). "To corroborate this functional association with phenotypic markers again in a more relevant system, we used activated CD4+ T cells, the primary targets of HIV-1 infection." (PMID 40911682, 2025). "GALT is infected in the early stages of HIV-1 infection, which disrupts gut integrity due to the massive depletion of CD4+ T lymphocytes, including T helper (Th) 17 and Th22 cells." (PMID 40733607, 2025). "After 4 days, quantification of HIV-1 infection rates revealed that bnAbs differentially affected the CD4+ T cell-mediated enhancement of macrophage infection, with effects strongly dependent on the viral strain used." (PMID 40130873, 2025). "Collectively, these findings indicate that GJB2 suppresses cell-to-cell HIV-1 transmission and thereby inhibits HIV-1 infection in target CD4+ T cells." (PMID 40980890, 2025). "Resting CD4 T cells are largely refractory to HIV-1 infection, yet these cells constitute an important reservoir of virus persistence." (PMID 38579727, 2024). "SAMHD1 is an intrinsic limiting factor that effectively prevents HIV-1 infection in macrophages, dendritic cells, and resting CD4+ T cells." (PMID 39240132, 2024). "A major obstacle to achieving a cure for HIV-1 infection is the persistence of latent viral reservoirs within long-lived CD4+ T cells." (PMID 39373537, 2024). "In summary, we determined that endogenous MARCH2 restricts HIV-1 infection in a CD4+ T cell specific manner, while MARCH8 inhibits HIV-1 in MDMs." (PMID 39074162, 2024). "The results confirmed HIV-1 infection with a viral load of 370,000 copies/ml, a CD4 count of 34 cells/μl, and a CD4/CD8 ratio of 0.1." (PMID 39640097, 2024). "CD4+ T cells are essential for the induction of an antiviral CD8+ T cell response, and the decline of the CD4+ T cell compartment following HIV-1 infection is accompanied by aberrant CD8+ T-cell immunity." (PMID 38548722, 2024). "A progressive decline of human immune cells, particularly CD4+ T lymphocytes, during HIV-1 infection was observed in infected animals reflecting the natural disease progression." (PMID 38399364, 2024). "It was observed that the majority of participants (34 out of 60, or 56.7%) had CD4+ T cell counts below 350 cells/mm3 at the time of diagnosis, indicating a late diagnosis of HIV-1 infection." (PMID 39772259, 2024). "We have demonstrated here that a significant number of genes involved in important immune system functions are differentially expressed in the CD4+ T cells of women compared to those of men during acute/early HIV-1 infection." (PMID 39902043, 2024). "CCR5 and CXCR4 were identified as co-receptors for HIV-1 entry into CD4+ T-cells, and human mannose receptor (hMR) was found to regulate CD4 independent HIV-1 infection of astrocytes, contributing significantly to HIV-1 induced neuropathogenesis." (PMID 39872863, 2024). "It is known that memory CD4+α4β7+ cells are an early target of HIV-1 infection following mucosal transmission." (PMID 38980725, 2024).
HIV-1 infection (continued). "CD4+ T cells are highly permissive to HIV-1 infection and are rapidly killed by active replication, while macrophages are infected at much lower levels and do not exhibit the cytopathic effect that is typical for CD4+ T cells." (PMID 38257827, 2024). "An interference at the early stages of HIV-1 infection, possibly disrupting the binding of viral gp120 to cell receptor CD4, was suggested to be the mechanism by which PCOSs exerted their anti-HIV-1 effect." (PMID 38666962, 2024). "HIV-1 infection is initiated by the interaction between the gp120 subunit in the envelope (Env) trimer and the cellular receptor CD4 on host cells." (PMID 39071380, 2024). "Two days post the HIV-1 infection, the number of viral particles in the supernatant was determined via titration on HeLa-CD4-LTR-β-gal cells." (PMID 38543476, 2024). "Upon HIV-1 infection of CD4+ T cells, the levels of NRON are decreased, leading to the elevation of NFAT expression in the nucleus and activation of the HIV-1 LTR." (PMID 38179937, 2024). "HIV-1 infection is initiated when the viral envelope (Env) glycoprotein binds to the CD4 and CCR5/CXCR4 expressed on the plasma membrane of the target immune cells." (PMID 38085100, 2024). "Here, we report that CPSF6 knock-out in primary CD4+ T cells leads to increased permissivity to HIV-1 infection due to broad transcriptional reprogramming." (PMID 39678349, 2024). "It is also known that in HIV-1 infection, there is an initial response through the activation and recruitment of CD4+ T cells, as occurs in the presence of EBV infection during infectious mononucleosis." (PMID 39066175, 2024). "Clinical features of TB presentation depend on the stage of HIV-1 infection and immunodeficiency, captured clinically by CD4+ T cell counts." (PMID 39181733, 2024). "These authors also showed that USP18 overexpression in HIV-1-derived memory CD4 T cells contributes to the loss of memory CD4 T cells themselves and other HIV-1-specific cells during the early phase of HIV-1 infection." (PMID 38932312, 2024). "Together, these results suggest that CPSF6 plays a role in modulating the innate immune response to HIV-1 infection in CD4+ T cells." (PMID 39678349, 2024). "Across multiple donors, incubation with epithelial cell-derived basolateral medium resulted in the productive HIV-1 infection of U87.CD4.CCR5 target cells." (PMID 39729509, 2024). "As a result of the cytopathic effects of the virus during acute HIV-1 infection, the frequency of CD4+ T cells declined by 13% during the first 14 d postinfection." (PMID 38278966, 2024). "CD4+ T cells with latent HIV-1 infection persist despite treatment with antiretroviral agents and represent the main barrier to a cure of HIV-1 infection." (PMID 38367616, 2024). "The objective of this review is to present these discoveries in their biological context to illustrate the mechanisms whereby Vpr supports HIV-1 infection in CD4+ T cells, whilst identifying findings that require validation in physiologically relevant models." (PMID 38543785, 2024). "To specifically examine the impact of augmenting miRNA-26a levels during HIV-1 infection, we nucleofected primary CD4+ T cells with miRNA-26a or control mimics and infected them with HIV-1." (PMID 39066239, 2024). "We next analyzed the viral determinants that contribute to the downregulation of miRNA-26a expression in CD4+ T lymphocytes during HIV-1 infection." (PMID 39066239, 2024). "Our previous data demonstrate that women, despite starting with higher numbers, lose CD4+ cells during HIV-1 infection at over twice the rate of men." (PMID 39902043, 2024). "Based on this, they evaluated the feasibility of the MG1 strategy in CD4+ T cells isolated from healthy donors, followed by HIV-1 infection." (PMID 38400005, 2024). "Downregulated LAMP2 was further confirmed in resting CD4+ T cells from patients with latent HIV-1 infection." (PMID 38750478, 2024).
HIV-1 infection (continued). "The incidence of HIV-1 infection in quiescent CD4+ T cells is typically low; but even minor alterations in these cells can result in increased susceptibility to HIV-1 infection." (PMID 39224601, 2024). "Differentially expressed proteins (DEPs) were confirmed in cell lines (U1 vs. U937, J-Lat (Jurkat cells latently infected with HIV-1) vs. Jurkat) and in primary resting CD4+ T cells collected from patients with HIV-1 infection." (PMID 38750478, 2024). "When cocultured with CD4+ T cells, CECs exacerbate HIV-1 infection/replication, by enhancing NF-κB activation in CD4+ T cells to facilitate HIV infection." (PMID 39474425, 2024). "Anti-Id mAb 1F7 was shown to selectively inhibit anti-HIV-1 cytotoxic CD8+ T cells against uninfected CD4+ T cells, potentially contributing to the prevention of CD4+ depletion and disease progression in human HIV-1 infection." (PMID 38628675, 2024). "PBMCs were obtained from healthy donors and proceeded to sort CD4+ T cells which were utilized as target cells for HIV-1 infection." (PMID 38468291, 2024). "CD4+ T cells constitute the main target for HIV-1 infection, being the most commonly infected cell type circulating in the blood, with HIV-1 preferentially infecting activated or memory T cells over naïve or quiescent T cells." (PMID 39205255, 2024). "Here, we performed RNA-seq profiling of miRNAs and mRNAs expressed in CD4+ T lymphocytes upon HIV-1 infection." (PMID 39066239, 2024). "As interactions with dendritic cells (DCs) can promote CD4+ T cell infection, and the functions of endometrial DCs are altered following menopause, whether DCs and natural killer cells contribute to post-menopausal increases in HIV-1 infection susceptibility warrants future study." (PMID 39872519, 2024). "As a consequence of HIV-1 infection, the number of CD4+ T cells is progressively declining in infected individuals, leading to systemic failure of the immune system, a hallmark of progression to AIDS." (PMID 38085100, 2024). "Others have described the antiviral function of human TRIM5α in HIV-1 infection of CD4+ T lymphocytes and during the clinical course of HIV-1 infection." (PMID 38548722, 2024). "Consistent with this, in the current study, α4β7 expressing CD4+ T cells were observed to be preferential targets of HIV-1 infection across all three FRT tissue types, particularly when co-expressed with CCR5." (PMID 39872519, 2024). "Taken together, these data suggest that the induction of APA through CFIm complex disruption results in broad transcriptional reprogramming and enhanced CD4+ T cell permissivity to HIV-1 infection." (PMID 39678349, 2024). "First, the widely used practice of bulk PBMC transduction with CAR constructs designed to treat HIV infection makes killer cells (CD4+) vulnerable to HIV-1 infection, which will certainly reduce the therapeutic effect." (PMID 39336102, 2024). "A monocytic cell line (THP-1 cells) or primary human monocytes were incubated with a CD4+ T cell line that expresses eGFP upon HIV-1 infection in the presence of antibodies and ADCP was measured as the accumulation of eGFP+ material by flow cytometry." (PMID 39466835, 2024). "Successful generation of latently infected primary CD4+ T cells ex vivo has relied on activating naïve or total CD4+ T cells through the T-cell receptor (TCR) as a prerequisite for permissive HIV-1 infection." (PMID 38580979, 2024). "Here, we describe a novel allosteric CXCR4 antagonist TIQ-15 which inhibits CXCR4-tropic HIV-1 infection of primary and transformed CD4 T cells." (PMID 39146384, 2024). "Current HIV-1 preventative or suppressive treatments consist of direct-acting antivirals that intervene in HIV-1 replication and are suitable in suppressing productive HIV-1 infection of CD4+ target cells." (PMID 39729509, 2024). "The physiological role of CD4 downmodulation subsequent to HIV-1 infection is to facilitate the release of virus particles from the cell membrane." (PMID 38787201, 2024).
HIV-1 infection (continued). "As combinations of medications termed antiretroviral treatment (or therapy) (ART) began to be used to treat HIV-1 infection in the mid-1990s, patients began showing rises in CD4+, CD45RO+ memory T cells." (PMID 38949029, 2024). "The role of ATF4 in autophagy and apoptosis is explored as in the context of HIV-1 infection programmed cell deaths contribute to the depletion of CD4 T cells." (PMID 38534416, 2024). "Dendritic cells, relative to macrophages and activated CD4+ T-cells, are the most resistant to HIV-1 infection but are productively infected." (PMID 39205287, 2024). "Here, we study the functional role of E3 ubiquitin ligases in the context of HIV-1 infection in physiologically relevant primary CD4+ T cells isolated from healthy human donors." (PMID 38411080, 2024). "We previously showed that knock-in-based expression of the fusion inhibitory peptides MT-C34 or 2P23 fully protected primary CD4 human T lymphocytes from HIV-1 infection." (PMID 39336102, 2024). "This study elucidated the influence of Vpr on the global methylation patterns of primary CD4 + T cells during HIV-1 infection." (PMID 38671522, 2024). "Corroborating a crucial role of CD4 in trogocytosis-mediated enhanced HIV-1 infection, we observed an accumulation of CD4 in CD32+ plasma membrane patches that co-localized with HIV-1 GFP particles." (PMID 38579727, 2024). "In this study, we conducted an assessment of the impact of Vpr on DNA methylation in primary CD4 + T cells during HIV-1 infection, utilizing WGBS." (PMID 38671522, 2024). "The main mechanism of SIR is the downmodulation of the CD4 receptor during a productive HIV-1 infection of CD4+ T cells." (PMID 38787201, 2024). "The high levels of viremia characteristic of untreated HIV-1 infection are sustained by continuous rounds of infection and turnover of CD4+ lymphocytes." (PMID 39466835, 2024). "In contrast to previous findings, MARCH2 RNA levels in all cell types we tested (H9, THP-1, primary CD4+ T cells and MDMs) were unaffected by HIV-1 infection and IFN-β treatment." (PMID 39074162, 2024). "In HIV-1 infection, CD4+T cells exhibited a skewed maturation from naive (CD45RA+CCR7+) and central memory (CD45RA−CCR7+) toward the effector memory (CD45RA–CCR7–) compartment." (PMID 38267841, 2024). "Together, these results show distinct methylation profiles between monocytes and CD4+ T cells in the acute versus chronic stages of HIV-1 infection." (PMID 38466776, 2024). "However, α4β7 expressing CD4+ T cells isolated from the EM of post-menopausal remained significantly more susceptible to HIV-1 infection relative to those of pre-menopausal patients, suggesting that increased HIV-1 infection susceptibility was instead driven by other unknown factors." (PMID 39872519, 2024). "MDMs are more refractory to HIV-1 infection compared to CD4+ T cells, making it challenging to observe VCCs." (PMID 39439384, 2024). "HIV-1 infection can induce hyperactivation of the actin depolymerization factor cofilin in both infected cells and resting bystander CD4+ T-cells." (PMID 38500818, 2024). "The standard treatment for HIV-1 infection is combination antiretroviral therapy with two or more antiretroviral agents, which can efficiently reduce plasma viral loads and maintain CD4 + T-lymphocytes." (PMID 38741006, 2024). "DEPs were confirmed in two types of HIV-1-latent cells (U1 vs. U937, and J-Lat vs. Jurkat), as along with resting CD4+ T cells from patients with HIV-1 infection." (PMID 38750478, 2024). "Its targeting by miRNAs in monocytes and resting CD4+ T cells partly explains how these cells are refractory to HIV-1 infection." (PMID 38790203, 2024). "Current knowledge on T-cell metabolism in HIV-1 infection suggests that HIV-1 takes advantage of the glycolytic process in CD4+ T cells to infect them and to boost viral replication." (PMID 38534416, 2024).